BARX2 (BARX homeobox 2)
Description:
Transcription factor. Binds optimally to the DNA consensus sequence 5'-YYTAATGRTTTTY-3'. May control the expression of neural adhesion molecules such as L1 or Ng-CAM during embryonic development of both the central and peripherical nervous system. May be involved in controlling adhesive processes in keratinizing epithelia (By similarity).
Tractability: PROTAC: ubiquitination databases record sites on it.
Gene: Protein-coding gene on chromosome 11 (129,375,848 to 129,452,279, forward strand). Ensembl gene ENSG00000043039.
Subcellular location: Nucleus
Subcellular location (Human Protein Atlas): Nucleoplasm; Cytosol; Golgi apparatus
Gene Ontology:
Molecular function: DNA binding; DNA-binding transcription activator activity, RNA polymerase II-specific; protein binding; RNA polymerase II transcription regulatory region sequence-specific DNA binding; sequence-specific double-stranded DNA binding; DNA-binding transcription factor activity, RNA polymerase II-specific; chromatin binding; DNA-binding transcription factor activity; sequence-specific DNA binding
Biological process: positive regulation of transcription by RNA polymerase II; regulation of transcription by RNA polymerase II; regulation of DNA-templated transcription
Cellular component: nucleoplasm; chromatin; nucleus; transcription regulator complex
Genetic constraint (gnomAD): Loss-of-function variants: 12 observed, 26.66 expected, observed/expected ratio (o/e) 0.45, 90% interval 0.29 to 0.73. The upper end of that interval is the gene's LOEUF score, 0.73, which puts it in group 2 of 6, group 1 being the genes least tolerant of losing a copy. Missense variants: 360 observed, 371.55 expected, observed/expected ratio (o/e) 0.97, 90% interval 0.89 to 1.06. Synonymous variants: 137 observed, 153.15 expected, observed/expected ratio (o/e) 0.89, 90% interval 0.78 to 1.03.
Homologues: Orthologues: chimpanzee BARX2 (100% identical), macaque BARX2 (97% identical), dog BARX2 (92% identical), rabbit BARX2 (89% identical), mouse Barx2 (89% identical), rat Barx2 (89% identical), pig BARX2 (86% identical), guinea pig BARX2 (78% identical), tropical clawed frog barx2 (70% identical), zebrafish barx2 (66% identical), Caenorhabditis elegans ceh-30 (22% identical), Caenorhabditis elegans ceh-31 (21% identical), and 2 more. Paralogues in human: BARX1 (38% identical), BARHL1 (29% identical), BARHL2 (28% identical).
Diseases named in the same sentence as BARX2 in open-access papers:
BARX2 is named in the same sentence as 46 diseases in open-access papers, as found by Europe PMC text mining. Sharing a sentence is not in itself a finding about the gene and the disease. The quoted sentences say what the papers report.
breast carcinoma (7 papers, 2012 to 2023). "Furthermore, among 150 breast cancer risk regions identified by genome-wide association studies, several ERGs identified in this study (BARX2, CBX6, KCNN4, MYEOV, PDZK1 in 300 ERGs) were included as the targets for cancer drivers, transcription factors, and signaling proteins." (PMID 35976950, 2022). "RBM15, regulated by BARX2 and ER, has been reported to affect cell growth and invasion in breast cancer samples." (PMID 37686507, 2023). "The coordination of BARX2 with ER was suggested to regulate the growth, survival, and invasion of breast cancer cells." (PMID 35976950, 2022). "Elevated expression of Barx2 inhibits cell growth, survival, and invasion pathways that are critical to breast cancer progression." (PMID 27533254, 2016). "However, BARX2 has been demonstrated to serve as an anti-oncogene in several malignant tumors, including breast cancer and ovarian cancer." (PMID 35200157, 2022). "However, as reported in breast cancer, Barx2 could also serve as an oncogene, promoting cell growth and invasion." (PMID 27533254, 2016). "Moreover, focal Barx2 expression was observed at sites undergoing epithelial-mesenchymal transition and its aberrant expression has been reported in some malignant cancers with poor prognosis, such as ovarian cancer, hepatocellular carcinoma, and breast cancer." (PMID 27533254, 2016). "It has been shown, BARX2 and estrogen receptor-alpha (ESR1) coordinately regulate the production of alternatively spliced ESR1 isoforms and control breast cancer cell growth and invasion." (PMID 22383897, 2012). "BARX2 plays a negative role in regulating the canonical Wnt/β-catenin pathway and serves as an anti-oncogene in non-small-cell lung cancer, colorectal cancer, hepatocellular carcinoma, breast cancer and ovarian cancer." (PMID 35200157, 2022). "Barx2 increased expression of both ESR1 isoforms, the estrogen-responsive genes (SOX5, RBM15 and Dynein), the tissue inhibitor of metalloproteinase (TIMP) genes (TIMP1 and TIMP3), and MMP-9, all of which promote breast cancer cell growth, survival, and invasion." (PMID 27533254, 2016).
hepatocellular carcinoma (4 papers, 2016 to 2023). A malignant tumor that arises from hepatocytes. "“Mutations” and “amplifications” of the BARX2 gene were found to be the main alterations in all cases of hepatocellular carcinoma." (PMID 37161008, 2023). "We used the TISCH2 database to analyse BARX2 expression in different cell types from different hepatocellular carcinoma datasets." (PMID 37161008, 2023). "Here, we conducted an in-depth study on the expression of BARX2 in hepatocellular carcinoma and its prognostic value." (PMID 37161008, 2023). "In view of the prognostic significance of BARX2 expression in LIHC and the unclear mechanism of action of BARX2 in hepatocellular carcinogenesis, we focused on investigating the biological role of BARX2 in hepatocellular carcinoma." (PMID 37161008, 2023). "The results showed that BARX2 expression was higher in regulatory T cells (Tregs), mast cells (Mast) and epithelial cells in various hepatocellular carcinoma datasets." (PMID 37161008, 2023). "MiR-942 targeted RRM2B to affect cell growth in hepatocellular carcinoma and regulated BARX2 to modulate NSCLC cell progression." (PMID 35230201, 2022). "In primary hepatocellular carcinoma, low expression of Barx2 is significantly correlated with tumor size, tumor differentiation, clinical stage, metastasis, and relapse, serving as an independent biomarker for adverse survival outcomes." (PMID 27533254, 2016). "Therefore, we aimed to study the biological role of BARX2 in hepatocellular carcinoma." (PMID 37161008, 2023). "However, the role of BARX2 in hepatocellular carcinoma is very poorly understood." (PMID 37161008, 2023). "In primary hepatocellular carcinoma, the expression of Barx2 had a negative correlation with markers of EMT, providing evidence that its low expression level in hepatocellular carcinoma was significantly correlated with tumor metastasis." (PMID 27533254, 2016).
ovarian carcinoma (4 papers, 2012 to 2022). A malignant neoplasm originating from the surface ovarian epithelium. "BARX2 also acts in a tumor suppressor and loss of heterozygosity of this gene, lead to poorer survival in patients with ovarian cancer." (PMID 22383897, 2012). "In ovarian cancer, Barx2 is expressed in the ovarian surface epithelium, where it induces the expression of cadherin 6, a functional suppressor of ovarian cancer progression." (PMID 27533254, 2016). "There were two downregulated transcription factors (BARX2 and CDX2), a glutathione regulating enzyme (GGT6) and a serine protease that correlates with improved survival in ovarian cancer (PRSS16)." (PMID 31052165, 2019).
colorectal cancer (3 papers, 2022 to 2023). A primary or metastatic malignant neoplasm that affects the colon or rectum. "The results showed that the cell lines with the highest expression of the BARX2 gene were breast and colorectal cancer cell lines." (PMID 37161008, 2023). "Downregulation of BARX2 has been verified to predict the poor survival in patients with colorectal cancer." (PMID 35037835, 2022).
non-small cell lung carcinoma (3 papers, 2021 to 2022). A group of at least three distinct histological types of lung cancer, including non-small cell squamous cell carcinoma, adenocarcinoma, and large cell carcinoma. "Under the condition of non-small-cell lung cancer, miR-942 elevated cell migration, invasion, and angiogenesis, which was reversed by BARX2 overexpression." (PMID 35037835, 2022). "Besides, BARX2 expression exhibits an inverse correlation with advanced tumor, node, metastases stage and a high level of Ki67 in patients with non-small cell lung carcinoma." (PMID 35037835, 2022). "It is reported that downregulation of Barx2 promotes aerobic glycolysis and predicts a poor prognosis in non-small cell lung carcinoma (NSCLC)." (PMID 34368114, 2021).
bladder cancer (2 papers, 2022 to 2023). "BARX2 partially abrogated the tumorpromoting effects of circSHPRH knockdown on proliferation, migration, and invasion in bladder cancer cells." (PMID 37627900, 2023). "The overexpression of BARX2 significantly repressed the viability and invasion of bladder cancer cells." (PMID 37627900, 2023).
gastric cancer (2 papers, 2016 to 2022). A primary or metastatic malignant neoplasm involving the stomach. "Moreover, BARX2 was downregulated by CpG Island methylation and was linked to repressed gastric cancer cell proliferation and invasion." (PMID 35037835, 2022). "Using quantitative real-time PCR, Western blotting, and immunohistochemistry, we found that Barx2 is expressed at lower levels in human gastric cancer (GC) tissues than in adjacent normal mucosa." (PMID 27533254, 2016).
lung adenocarcinoma (2 papers, 2021 to 2023). A carcinoma that arises from the lung and is characterized by the presence of malignant glandular epithelial cells. "BARX2 expression in lung adenocarcinoma (LUAD) was positively associated with almost all tumour biological behaviours, such as angiogenesis, differentiation, EMT and hypoxia." (PMID 37161008, 2023). "For instance, circFBXW7 played a tumor-inhibitory role in lung adenocarcinoma via sponging miR-942-5p and increasing the BARX homeobox 2 (BARX2) expression." (PMID 34537072, 2021).
acute myeloid leukaemia (1 paper, 2023). "The lowest BARX2 expression was observed in acute myeloid leukaemia (LAML), pheochromocytoma and paraganglioma (PCPG), and uveal melanoma (UVM), and BARX2 expression in LIHC was at a moderate to low." (PMID 37161008, 2023).
cervical squamous cell carcinoma (1 paper, 2023). A squamous cell carcinoma arising from the cervical epithelium. "The highest BARX2 level was observed in cervical squamous cell carcinoma and endocervical adenocarcinoma (CESC), head and neck squamous cell carcinoma (HNSC) and kidney renal clear cell carcinoma (KIRC)." (PMID 37161008, 2023).
chronic granulocytic leukaemia (1 paper, 2023). "Cell lines derived from the haematologic system (e.g. chronic granulocytic leukaemia) showed relatively low BARX2 expression, while lower BARX2 expression was observed in LIHC cell lines." (PMID 37161008, 2023).
colon adenocarcinoma (1 paper, 2023). "In contrast, BARX2 expression was downregulated in breast invasive carcinoma (BRCA), colon adenocarcinoma (COAD), head and neck squamous cell carcinoma (HNSC), rectum adenocarcinoma (READ), and thyroid carcinoma (THCA)." (PMID 37161008, 2023).
glioblastoma (1 paper, 2023). The most malignant astrocytic tumor (WHO grade IV). "BARX2 expression in glioblastoma multiforme (GBM) and uveal melanoma (UM) was negatively associated with almost all tumour biological behaviours, such as DNA repair, DNA damage, invasion and metastasis." (PMID 37161008, 2023).
liver cancer (1 paper, 2023). An epithelial or non-epithelial malignant neoplasm that arises from the liver. "Our comprehensive bioinformatic analysis of BARX2 expression in different cell types from different liver cancer datasets showed that BARX2 expression was higher in regulatory T cells (Tregs), mast cells (Mast) and epithelial cells." (PMID 37161008, 2023).
lupus nephritis (1 paper, 2023). Glomerulonephritis in the context of systemic lupus erythematosus. "Additionally, for ‘response to cyclophosphamide in systemic lupus erythematosus with lupus nephritis’ (12 genes in GWAS), we found two overlap genes, BARX2 and HIPK2." (PMID 37048133, 2023). "A SNP related to lupus nephritis (LN) has been found close to BARX2." (PMID 37048133, 2023).
medullary thyroid carcinoma (1 paper, 2017). "For example, loss of Barx2 promotes the malignant differentiation of medullary thyroid carcinoma and is associated with poor prognosis." (PMID 29069753, 2017).
oral squamous cell carcinoma (1 paper, 2022). "Consistently, BARX2 expression was downregulated in the vast majority of oral squamous cell carcinoma, and this downregulation was more pronounced in tumors with advanced nodal metastasis." (PMID 35037835, 2022).
schizophrenia (1 paper, 2025). A major psychotic disorder characterized by abnormalities in the perception or expression of reality. "The similar expression pattern to the affected BAs implies the possible functions of Barx2 in schizophrenia." (PMID 40685676, 2025).
tumor (13 papers, 2009 to 2024). "In residual tumours, low expression of BARX2 was significantly associated with stage R0, while stage R1 was associated with high expression of BARX2." (PMID 37161008, 2023). "The present study, based on the TCGA and GEO databases, shows the multifaceted prognostic impact of BARX2 overexpression on OS in certain tumour types, with higher BARX2 expression associated with better OS in KIRC, KIRP, LIHC, and SKCM and poorer OS in BLCA, KICH, LUAD, PAAD, and UVM." (PMID 37161008, 2023). "In addition, residual tumour was associated with increased expression of BARX2 (P < 0.001." (PMID 37161008, 2023). "Importantly, BARX2 overexpression was associated with T stage and residual tumour." (PMID 37161008, 2023). "Dysregulation of BARX2 and its oncogenic role in the development of various tumours such as ovarian, gastric and lung cancers have been reported." (PMID 37161008, 2023). "The results of genetic alteration characteristics of the BARX2 gene, such as frequency, mutation type and copy number alteration (CNA), among different tumours in the TCGA database are displayed in the “Cancer Types Summary” module of the cBioPortal website." (PMID 37161008, 2023). "We investigated the genetic alterations in the BARX2 gene in different types of tumours in the TCGA dataset on cBioPortalWeb." (PMID 37161008, 2023). "We used it to analyse the expression of BARX2 in different types of tumour samples and to download box plots from the UALCAN website." (PMID 37161008, 2023). "The TIMER, EPIC, QUANTISEQ, XCELL, MCPCOUNTER, CIBERSORT, CIBERSORT-ABS and TIDE algorithms were applied to explore the correlations between BARX2 expression and invasion of different immune cells in tumour tissues from multiple cancers." (PMID 37161008, 2023). "We investigated the relationship between BARX2 expression and prognosis in cancer patients based on a basic assessment of BARX2 expression in different tumours." (PMID 37161008, 2023). "Using the TCGA, the mRNA levels of BARX2 were also investigated in 33 tumour tissues, and all cancers expressed BARX2." (PMID 37161008, 2023). "Subsequently, we compared BARX2 expression levels between tumour and normal samples from 33 cancers in the TCGA and GTEx datasets." (PMID 37161008, 2023). "In conclusion, this study reveals a tumor-suppressing role of circSHPRH in BCa progression by sponging miR-942 and upregulating BARX2 expression." (PMID 35200157, 2022). "An in vivo tumor metastasis model was generated by tail vein injection of tumor cells, and we observed that overexpression of BARX2 also inhibited tumor metastasis to the lung in vivo by HE staining." (PMID 35037835, 2022). "BARX2 is involved in regulating squamous epithelium and craniofacial development and is a suppressor of several type of neoplasms." (PMID 27542258, 2016). "Although BARX2 expression reduces the tumor burden of xenografts, it is unable to decrease the mortality of animals significantly, its targets and functional mechanisms in OSCC tumors remain to be identified." (PMID 27542258, 2016). "Further verified by the higher expression of cell proliferation biomarkers Ki-67 and PCNA with IHC staining of the tumor xenografts, we demonstrated that Barx2 inhibits GC cell proliferation in vitro and in vivo." (PMID 27533254, 2016). "Further study in vivo demonstrated that Barx2 suppresses xenograft tumor formation and prohibits tumor tumor cell invasive activity in nude mice." (PMID 27533254, 2016). "Barx2 was greatly reduced in the majority of GC tumor tissues with strong staining in only 17/264 (6.4%) specimens, weak staining in 82/264 (31.1%) specimens, and negative staining in 165/264 (62.5%) specimens." (PMID 27533254, 2016). "Further investigation in vivo showed that SGC-7901 cells with Barx2 knocked down generated larger subcutaneous xenografts, as measured by tumor weights and volumes in nude mice compared with the control (P<0.05)." (PMID 27533254, 2016).